DPP4 (dipeptidyl peptidase 4)
Diseases named in the same sentence as DPP4 in open-access papers (continued):
Sharing a sentence is not in itself a finding about the gene and the disease.
diabetes (continued). "Vildagliptin, a DPP-4 inhibitor widely used for the treatment of type 2 diabetes mellitus (T2DM), shows beneficial effects on endothelial function." (PMID 26312070, 2015). "The DPP4 inhibitors are now well established as hypoglycaemic agents for use in patients with type 2 diabetes mellitus." (PMID 26509887, 2015). "Sitagliptin, a dipeptidyl peptidase-4 (DPP-4) inhibitor, is currently used to achieve glycemic targets in patients with type 2 diabetes mellitus (T2DM)." (PMID 24607023, 2014). "Three classes of anti-diabetes treatment were covered by the 5 studies fulfilling the inclusion criteria: DPP-4 inhibitors (3 studies), GLP-1 analogues (1 study) and SGLT2 inhibitors (1 study)." (PMID 25006351, 2014). "The observation that Saxagliptin restores the function of PACs from T2D patients represents an additional step toward a better understanding of the pathobiology of DPP-4 in diabetes." (PMID 24886621, 2014). "This study aims to analyse the utilization patterns of DPP-4 inhibitors, factors that influenced the choice of agent, and the rationale for treatment with DPP-4 inhibitors in patients with type 2 diabetes mellitus." (PMID 25258626, 2014). "The dipeptidyl-peptidase-IV (DPP-4) inhibitors, including sitagliptin, are used for the treatment of type 2 diabetes mellitus (T2DM)." (PMID 24884787, 2014). "This retrospective study was conducted to address the utilization pattern of DPP-4 inhibitors and factors that influence choice in type 2 diabetes mellitus patients." (PMID 25258626, 2014). "Diabetes and hyperglycemia increase the DPP-4 protein level and enzymatic activity in blood and tissues." (PMID 25140306, 2014). "Clinical use of GLP-1 for diabetes was limited by its rapid degradation by dipeptidyl peptidase-4 (DPP-4) and other peptidases." (PMID 25278825, 2014). "The dipeptidyl peptidase-4 inhibitor sitagliptin, a new anti-diabetic medicine, is effective in treating type 2 diabetes mellitus by increasing the activation and duration of action of glucagon-like peptide-1." (PMID 24490809, 2014). "Among the major test results, “Korean prevalence of diabetes and evaluations of dipeptidyl peptidase-4 inhibitor use” demonstrated that the estimate on diabetes prevalence using sample data aligned with that of population-analysis." (PMID 25078381, 2014). "In 2006, a new class of antidiabetic agents, dipeptidyl peptidase-4 (DPP-4) inhibitor, was approved for the treatment of type 2 diabetes mellitus." (PMID 25140306, 2014). "Dipeptidyl peptidase-4 (DPP-4) inhibitors are effective in improving metabolic parameters in patients with type 2 diabetes mellitus (T2DM) but little is known about its cardiovascular effects." (PMID 25285158, 2014). "In a recent study on healthy young people DPP4 activity is correlated with the clinical parameters of obesity and/or diabetes." (PMID 23853775, 2013). "Linagliptin, one of the five dipeptidyl peptidase-4 inhibitors available, has recently entered the market both in the US and in most European countries for treatment of type 2 diabetes mellitus." (PMID 23550180, 2013). "Albeit preliminary and descriptive in nature, these results set the stage for further experimental studies aimed to test the potential involvement of an excess of DPP4 in the pathogenesis of LVD in diabetes." (PMID 24099410, 2013). "Upregulation of DPP-4 expression in renal glomeruli occurs during inflammation and usually accompanies the development of diabetes-induced glomerulosclerosis." (PMID 24089613, 2013). "For example, DPP4 is a serine protease, that specifically degrades incretin hormones; thus, its inhibitor is considered as a useful drug for type 2 diabetes mellitus." (PMID 24360150, 2013). "Dipeptidyl peptidase-4 (DPP-4) inhibitors modulate incretin hormones and exert anti-diabetic effects in type 2 diabetes mellitus." (PMID 24188631, 2013).
diabetes (continued). "Previous data, in experimental models, suggest that both incretin mimetic agents and DPP-4 inhibitors agonists suggest a potentially beneficial role in diabetes-affected wound healing." (PMID 23197976, 2012). "DPP-4 inhibitors are considered effective for the treatment of type 2 diabetes mellitus in Asian patients, including Japanese patients, who often have insufficient insulin secretion, in contrast to Caucasian patients who usually have insulin resistance." (PMID 22867630, 2012). "The glucagon-like peptide-1 receptor (GLP-1R) agonists and dipeptidyl peptidase-4 (DPP-4) inhibitors have become important options for the management of patients with type 2 diabetes mellitus." (PMID 22390369, 2012). "DPP-4 inhibitors are oral antihyperglycemic drugs that have recently become available for diabetes treatment." (PMID 22867630, 2012). "Incretin-based therapies have established a foothold in the diabetes armamentarium through the introduction of oral dipeptidyl peptidase-4 inhibitors and the injectable class, the glucagon-like peptide-1 receptor agonists." (PMID 21707956, 2012). "The only obstacle which prevents the native molecule to be used as a therapeutic agent for the treatment of diabetes is that GLP-1 is rapidly degraded within minutes by DPP-4." (PMID 21673955, 2011). "In conclusion, a continuous flow study design has been applied to investigate three distinct areas of interest related to the novel DPP-4 inhibitor linagliptin in Japanese diabetes patients." (PMID 19732457, 2009). "Although it seems likely that some of the newly discovered diabetes genes act in a pathway that is targeted by GLP1 receptor-agonists or DPP-4 inhibitors, more research into both the mechanisms of the medication and the function of the genes is needed." (PMID 19794883, 2009). "Elements as dysregulation of dipeptidyl peptidase-4 (DPP-4), insulin growth factor-1 (IGF-1), advanced glycation end products (AGEs), and insulin resistance increase the risk of developing severe aortic stenosis in individuals with diabetes mellitus." (PMID 40943088, 2025). "From a multi-target perspective, the elevation in cAMP levels may not solely result from GLP-1R activation but could also involve other diabetes-related therapeutic targets such as DPP4, GIPR, and GCGR." (PMID 41373699, 2025). "Diabetes increases the AGE/RAGE axis-related DPP-4 activity." (PMID 40429343, 2025). "Glucagon-Like Peptide 1 (GLP-1) receptor agonists and Dipeptidyl Peptidase 4 (DPP-4) inhibitors, commonly employed in diabetes management, have been shown to reduce cardiovascular risk in patients, thereby potentially mitigating the deleterious effects of COPD." (PMID 41348723, 2025). "Thus, DPP-4 inhibition has become a well-established strategy for the prevention and treatment of diabetes, and DPP-4 inhibitors are widely used as antidiabetic drugs." (PMID 41517158, 2025). "This study presents an efficient approach combining virtual screening and experimental validation, offering a structural and mechanistic foundation for the development of natural DPP-4 inhibitory peptides as candidates for functional foods or adjunct diabetes therapies." (PMID 40509444, 2025). "Recent studies have suggested that anti-diabetes targeting the glucagon-like protein receptor 1, dipeptidyl peptidase-4 inhibitors (DPP4i), may have a preventive effect on dementia." (PMID 38860903, 2025). "For instance, insulin sensitizers (Thiazolidinediones and Biguanides), insulin secretagogues (Meglitinide and Sulfonylureas derivatives), dipeptidyl peptidase-4 (DPP-4) inhibitors, α-glucosidase inhibitors, and exogenous insulin have been extensively used to treat diabetes mellitus." (PMID 40722869, 2025).
diabetes (continued). "However, in the absence of an active comparator generally regarded as cardiovascularly neutral, such as DPP‐4 inhibitors, it remains unclear whether low‐affinity sulfonylureas exert neutral effects and whether high‐affinity sulfonylureas increase cardiovascular risk in patients with diabetes." (PMID 41017568, 2025). "DPP-4 inhibitors may serve as immunomodulatory agents in COVID-19, potentially reducing the mortality risks in patients with diabetes or other comorbid conditions by mitigating respiratory inflammation." (PMID 40509444, 2025). "Among the therapeutic options for the treatment of hyperglycemia, thiazolidinediones (TZDs) represent a significant breakthrough in the history of diabetes management, preceding the discovery of DPP-4 inhibitors, SGLT2 inhibitors, and glucagon-like peptide-1 receptor (GLP-1R) agonists." (PMID 41302503, 2025). "DPP-4 inhibitors are the latest addition in the management of type 2 diabetes mellitus." (PMID 40734861, 2025). "Notably, GLP-1 analogs, SGLT2 inhibitors, and DPP-4 inhibitors have been explored in feline and canine models, potentially providing translational insights applicable to human diabetes therapy." (PMID 41012437, 2025). "DPP-4 inhibitors significantly reduced daily insulin requirements, particularly bolus doses, and postprandial blood glucose (by −34.40 mg/dL), especially in patients with a BMI < 25 kg/m2 and diabetes duration <3 years." (PMID 41026724, 2025). "In diabetes care, pharmacogenomics has shown promise in tailoring treatments involving commonly prescribed agents such as metformin, sulfonylureas, thiazolidinediones, and dipeptidyl peptidase-4 (DPP-4) inhibitors, among others." (PMID 41149843, 2025). "DPP-4 inhibitors are now established agents for glycaemic control in diabetes." (PMID 41560728, 2025). "Accordingly, DPP-4 represents a promising target for the treatment of diabetes." (PMID 41560728, 2025). "However, DPP-4 inhibitors have been found to provide some benefit in patients with diabetes and HFpEF." (PMID 40141772, 2025). "Background and Objectives: Neuropeptide Y (NPY) family peptides and dipeptidyl peptidase-4 (DPP-4) are involved in gastrointestinal regulation and may contribute to obesity and type 2 diabetes mellitus (T2DM) pathophysiology." (PMID 40142315, 2025). "GLP1 analogs, TZDs, SGLT2 inhibitors, DPP4 inhibitors, SU and insulin show overall benefits for amyloid and tau pathologies, neuron health, inflammatory and vascular alterations, alongside improved cognition in animal models mimicking AD and/or diabetes." (PMID 41146261, 2025). "Additionally, we identified three compounds that effectively targeted a protein (DPP4) involved in diabetes (PDB ID: 4A5S)." (PMID 39865621, 2025). "Search terms included a combination of MeSH terms and keywords: “diabetes mellitus,” “type 2 diabetes mellitus,” “DPP-4 inhibitor,” “Dipeptidyl peptidase 4 inhibitors,” “vildagliptin,” “sitagliptin,” “linagliptin,” “alogliptin,” “HbA1c,” “blood glucose levels,” and “adverse events." (PMID 40901275, 2025). "In addition, the extract showed lower levels of glycemia and lipids compared to metformin, since the mechanisms of these are different, and it has been reported that DPP4 inhibitors allow better control of diabetes than metformin." (PMID 40265815, 2025). "DPP4 can hydrolyze many endogenous peptides, resulting in the activation or inactivation of endogenous peptides, and has long attracted attention as a therapeutic target for diabetes mellitus." (PMID 39949782, 2025). "A study predicting the next prescribed diabetes drugs for 161,497 patients with diabetes using sequential pattern mining demonstrated an accuracy of 89.1%‐90.5% in guessing from 37 drug classes (eg, DPP-4 inhibitor) and 63.5%‐64.9% accuracy in guessing from 43 drugs (eg, algliptin)." (PMID 40456113, 2025).
diabetes (continued). "DPP4 inhibitors also improve social interaction deficits and reduce depressive-like behaviors in various animal models of depression, including chronic restraint stress, chronic unpredictable mild stress, high fat diet, diabetes and morphine withdrawal." (PMID 40490517, 2025). "Furthermore, elevated glucose levels stimulate the expression of ACE2, glycosylated ACE2, and TMPRSS2 in cardiomyocytes from individuals with diabetes, as well as DPP4 expression in the liver." (PMID 40431631, 2025). "A Phase IV study was conducted to evaluate the safety and efficacy of a Fixed Dose Combination (FDC) of Remogliflozin, Metformin and Vildagliptin (RMV) in Type 2 Diabetes Mellitus (T2DM) patients uncontrolled on Metformin plus SGLT2 inhibitor or Metformin plus DPP4 inhibitor dual therapy." (PMID 39690416, 2024). "Similarly, we observed that diabetes-enhanced DPP4 activity in the plasma was closely related to diabetes-induced adipose inflammation and glucose intolerance." (PMID 39125659, 2024). "This study may provide a valuable starting point; however, subsequent experiments are necessary to validate the efficacy and safety of phytochemicals as DPP-4 inhibitors for the treatment of diabetes." (PMID 38675143, 2024). "Our findings suggest that those compounds might be possible candidates for developing novel inhibitors targeting DPP-4 for treating diabetes." (PMID 38675143, 2024). "Phytochemicals have shown promise as potential DPP-4 inhibitors for managing diabetes." (PMID 38675143, 2024). "Through molecular processes of bacterial DPP-4 activities, periodontopathic bacteremia could exacerbate diabetes mellitus." (PMID 38337597, 2024). "DPP-4 inhibitors or gliptins are increasingly used for the treatment of type 2 diabetes mellitus." (PMID 39526061, 2024). "The comparative effectiveness of glucagon-like peptide-1 (GLP-1) agonists, dipeptidyl peptidase-4 (DPP-4) inhibitors, and sulfonylureas on the risk of dementia in older individuals with type 2 diabetes mellitus (T2DM) is unknown." (PMID 39429814, 2024). "Therefore, identification of plant-based natural inhibitors of DPP-4 would help in eradicating diabetes worldwide." (PMID 38675143, 2024). "In addition, the presence of diabetes was an independent contributing factor for higher DPP4 activity." (PMID 39507187, 2024). "The essential features of the 1-year and 3-year follow-up models were baseline eGFR, BUN, creatinine, triglyceride, age, gender, Hgb, CHOL, PLTs, albuminuria, diabetes disease, hypertension and related medications (eg, diuretics, insulin, dipeptidyl peptidase-4 and calcium channel blockers)." (PMID 38677774, 2024). "Inhibiting DPP-4 was anticipated as a potential new therapy for diabetes." (PMID 38675143, 2024). "Newer treatment modalities in diabetes, like GLP- 1 analogues, DPP-4 inhibitors, and bariatric surgical procedures, adress the topic of GV efficiently, and also investigating GV with the use of such drugs is promising in enhanced diabetes management." (PMID 38310479, 2024). "The current Research Society for the Study of Diabetes in India (RSSDI)-Endocrine Society of India (ESI) clinical practice guidelines recommend DPP-4 inhibitors as second-line therapy as an add-on to metformin if glucose control targets are not achieved with metformin monotherapy." (PMID 38975525, 2024). "Regarding concomitant drug use for diabetes, alpha-glucosidase inhibitors, dipeptidyl peptidase-4 inhibitors, glinides, glucagon-like peptide-1 agonists, and insulin were more commonly used as the albuminuria severity increased, while biguanides were less frequently used." (PMID 37955878, 2024). "In this context, particular attention is warranted regarding the potential role of sodium-glucose cotransporter-2 (SGLT2) inhibitors, thiazolidinediones and dipeptidyl peptidase 4 (DPP-4) inhibitors which are used in the management of diabetes and have been demonstrated to reduce insulin resistance." (PMID 39202319, 2024).
diabetes (continued). "After confirming the incretin secretion capacity of patients with DM1, we intended to clarify whether dipeptidyl peptidase 4 (DPP-4) inhibitor administration was appropriate in cases of DM1 with diabetes mellitus." (PMID 39274465, 2024). "Dipeptidyl peptidase-IV (DPP-4) enzyme inhibitors are a promising category of diabetes medications." (PMID 38887277, 2024). "Dipeptidyl peptidase-4 (DPP-4) inhibitors have emerged as an essential class of glucose-lowering drugs in managing diabetes, given their favorable profiles in terms of weight neutrality, low hypoglycemia risk, and, for many drugs in this class, ease of use in patients with varying renal function." (PMID 39768866, 2024). "The discovery of periodontopathic DPP-4-specific inhibitors and their use in patients with type 2 diabetes mellitus could work in conjunction to lower blood glucose levels since human DPP-4 inhibitors are less effective against bacterial DPP-4." (PMID 38337597, 2024). "The presence of diabetes was an independent contributing factor to higher DPP4 activity." (PMID 39507187, 2024). "Dipeptidyl peptidase 4 (DPP-4) inhibitors are commonly used drugs to treat diabetes." (PMID 38543024, 2024). "This study aimed to evaluate whether saxagliptin, a potent and selective DPP-4 inhibitor that is globally used for treating type 2 diabetes mellitus, binds to the nucleophiles in vitro." (PMID 38258116, 2024). "A study conducted on patients with diabetes mellitus type 2 (DM type 2) using SGLT2 inhibitors or DPP-4 inhibitors revealed that the rate of acute pancreatitis was significantly decreased in patients taking SGLT2 inhibitors than in those taking DPP-4 inhibitors." (PMID 38611003, 2024). "These enzymes are linked to diabetes-induced neurodegeneration by driving processes such as cholinergic deficiency (AChE), amyloid plaque formation (BACE-1), inflammation and oxidative stress (DPP-4), and tau pathology (GSK-3β)." (PMID 39766390, 2024). "Experimental researches on rats have recently demonstrated the DPP-4 inhibitory,anti-diabetic effects of terminalia arjuna The present study was done onsixty diagnosed cases of diabetes mellitus, randomly distributed into 2 groups, with each enrolling 30 patients." (PMID 40230891, 2024). "Therefore, our review aims to provide a comprehensive overview of the dermatological side effects of DPP-4 inhibitors in patients with diabetes based on the current knowledge." (PMID 38523307, 2024). "This suggests that DPP-4 inhibitors, which are commonly used for treating type 2 diabetes mellitus (T2DM), may offer therapeutic benefits beyond glycemic control, potentially mitigating bone resorption and reducing fracture risk." (PMID 39054499, 2024). "DPP4 inhibitors are effective drugs for the treatment of type 2 diabetes mellitus." (PMID 38379936, 2024). "This review explores inflammation's role in cardiac fibrosis and evaluates emerging anti-diabetic medications' effectiveness, such as SGLT2i, GLP1-RAs, and dipeptidyl peptidase-4 inhibitors (DPP4i), in preventing fibrosis in patients with diabetes post-acute MI." (PMID 38927520, 2024). "Furthermore, several cases developed BP as a consequence of treatment for other pathologies (such as dipeptidyl peptidase 4 inhibitors for diabetes treatment; BP due to oncological treatment with anti-HER-2 drugs)." (PMID 39200987, 2024). "For example, sulfonylurea, the first-choice drug for diabetes in the United Kingdom, is associated with weight gain, but dipeptidyl peptidase-4 inhibitors, which are widely used in Japan, are not." (PMID 36709979, 2024). "According to diabetes management guidelines, first-line therapy with metformin monotherapy is recommended, and if HbA1C target levels are not achieved, dual therapy with metformin plus sulfonylureas or DPP-4 inhibitors will be used." (PMID 39449943, 2024).